GDF15 (growth differentiation factor 15)
Diseases named in the same sentence as GDF15 in open-access papers (continued):
Sharing a sentence is not in itself a finding about the gene and the disease.
melanoma (continued). "High GDF15 serum levels were also correlated with poorer overall survival in melanoma patients." (PMID 36720918, 2023). "GDF15 expression was significantly increased in sunitinib-resistant melanoma cells." (PMID 36720918, 2023). "Based on in vitro pharmacological studies, mouse models and analyses of human melanoma patients, we show that the cytokine GDF-15 impairs LFA-1/β2-integrin-mediated adhesion of T cells to activated endothelial cells, which is a pre-requisite of T cell extravasation." (PMID 37474523, 2023). "Furthermore, inhibition of STAT3 decreased the expression of GDF15, and GDF15 silencing increased the sensitivity of melanoma cells to sunitinib." (PMID 36720918, 2023). "Consequently, patients with higher GDF-15 serum levels were more likely to die from melanoma (HR = 1.27, 95% CI [1.10;1.47] per ng/ml GDF-15, p = 0.001)." (PMID 37474523, 2023). "In patients with tumor-free stage III or unresectable stage IV melanoma, there was such a significant link between elevated GDF-15 serum levels and poor survival that the clinically well-established marker LDH was no longer statistically significant in the multivariate analyses." (PMID 32508832, 2020). "In melanoma where GDF-15 expression is induced by oncogenic V600EB-Raf and by microphthalmia-associated transcription factor (MITF), GDF-15 may be involved in angiogenesis." (PMID 32508832, 2020). "Correlations between GDF-15 and cancer progression have been described for colorectal, gastric, hepatocellular carcinoma, non-small cell lung cancer, urothelial/renal cell, ovarian, melanoma, breast, multiple myeloma, and oral cancers." (PMID 32508832, 2020). "In addition, western blots showed that transfection of both miRNA mimics significantly decreased endogenous GDF15 expression in a melanoma cell line (P < 0.05)." (PMID 28806401, 2017). "Kluger and colleagues proposed a multiplex, plasma-based protein biomarker panel that included CEACAM, ICAM-1 (intercellular adhesion molecule 1), osteopontin, MIA (melanoma inhibitory activity), GDF-15 (growth differentiation factor 15), TIMP-1 (tissue inhibitor of metalloproteinase 1), and S100B." (PMID 27642217, 2016). "Interestingly, the expression of GDF15 was significantly higher in metastatic than in primary melanomas (one-way ANOVA, p < 0.0001)." (PMID 26540631, 2015). "In addition, activation of PTEN/PI3K/AKT signaling pathway by 740Y-P greatly reversed the influence of GDF15 on melanoma, indicating that GDF15 might affect the development of melanoma via targeting PTEN/PI3K/AKT signaling pathway." (PMID 38230211, 2024). "If GDF15 could regulate melanoma through targeting PTEN/PI3K/AKT signaling pathway remain unclear." (PMID 38230211, 2024). "Five genes (CXCL10, TNF, PIK3CD, PIK3R2, and CXCL1) of the TNF signalling pathway and seven genes (CXCL9, GDF15, BMP7, TNFRSF15, CXCL10, TNF, and CXCL1) of the cytokine–cytokine receptor pathway were commonly upregulated in melanoma cells." (PMID 39496484, 2024). "The present study evaluated the prognostic significance of serum GDF-15 and IL-6 levels in patients undergoing immunotherapy for advanced malignancies, including NSCLC, RCC, and malignant melanoma." (PMID 39766045, 2024). "In the present study, we demonstrated that knockdown of GDF15 remarkably inhibited the PTEN/PI3K/AKT signaling pathway and malignant melanoma." (PMID 38230211, 2024). "We further generated GDF15 knockout cells using CRISPR/Cas9 technology and found that GDF15 knockout sensitized melanoma cells to sunitinib." (PMID 36720918, 2023). "Mechanistically, BET inhibitors sensitize melanoma cells to sunitinib by inhibiting the BRD4/GDF15 axis and the BRD4/IL6/STAT3/GDF15 axis." (PMID 36720918, 2023). "Altogether, these findings suggest that BET inhibitor-mediated GDF15 inhibition plays a critical role in enhancing sunitinib sensitivity, indicating that BET inhibitors synergize with sunitinib in melanoma." (PMID 36720918, 2023).
melanoma (continued). "Therefore, GDF15 might be a potential therapeutic target in melanoma." (PMID 36720918, 2023). "In these melanoma metastases infiltrating CD3+ and CD8+ T cells were inversely correlated with GDF-15 tissue levels." (PMID 37474523, 2023). "For instance, the upregulated blood-based expression of osteopontin (OPN), S-100β, growth differentiation factor-15 (GDF-15), melanoma inhibitory activity (MIA) and B cell-activating factor (BAFF) were confirmed to have associations with the metastases of UM." (PMID 34070192, 2021). "Genes such as KRT14, GJA1, S100A7, S100A9, and EHF were higher in most melanomas while genes such as CITED-1, GDF15, QPRT, OCA2, c-MET and MME were more highly expressed in NHEM." (PMID 18442402, 2008). "This is consistent with a previous report indicating that GDF-15 silencing in melanoma cells did not influence tumor cell behavior in vitro but inhibited the tumor growth in immunocompetent mice by suppressing angiogenesis." (PMID 39283723, 2024). "Analysis using the GEPIA and TCGA databases revealed a negative correlation between GDF15 expression and survival rates in melanoma patients." (PMID 38230211, 2024). "Considering the antiapoptotic role of GDF15, it is reasonable to speculate that GDP15 leads to sunitinib resistance in melanoma by inhibiting apoptosis." (PMID 36720918, 2023). "For this reason, GDF15 was proposed as a diagnostic biomarker for early-stage lung cancer, and correlations between GDF15 and progression have been described for gastric, colorectal, hepatocellular, NSCLC, renal cell, melanoma, and oral cancers." (PMID 36472770, 2023). "A second (Tübingen-based) cohort with pre-treatment serum samples from 88 melanoma patients treated with the anti-PD-1 antibodies pembrolizumab or nivolumab confirmed the negative correlation between GDF-15 serum levels and success of anti-PD-1 treatment." (PMID 37474523, 2023). "To further investigate whether those candidate markers were clinically associated with tumors, we used tissue microarrays with human melanoma samples to examine TNC and GDF15 expression." (PMID 26540631, 2015). "For other genes, such as SPP-1, GDF15 (putative oncogenes), PITX-1 and CST6 (putative TSG), the major shifts in gene expression appear to occur at distinct but different times during the thickening of the primary melanoma tumors." (PMID 18442402, 2008). "Preclinical models further suggest that GDF15 inhibition might enhance the activity of bispecific T-cell engagers such as tebentafusp, which binds gp100 on GDF-15-secreting HLA-A2+ SK-MEL-5 melanoma cells, by restoring T-cell infiltration and improving tumor-specific immune responses." (PMID 40868185, 2025). "If GDF15 could regulate the progression of melanoma through affecting EMT process has not been reported." (PMID 38230211, 2024). "The lack of durable responses in ipilimumab-treated melanoma patients with high GDF-15 levels may be due to impaired trafficking of T cells into the tumor tissue." (PMID 37474523, 2023).
glioma (37 papers, 2014 to 2025). A benign or malignant brain and spinal cord tumor that arises from glial cells (astrocytes, oligodendrocytes, ependymal cells). "By screening differentially expressed genes, and performing WGCNA, LASSO, and multivariate Cox regression analyses, we identified risk hub genes (RAB42, SH2D4A, and GDF15) associated with glioma stemness, genomic heterogeneity, and the immune microenvironment." (PMID 37698534, 2023). "We found that high expression level of GDF15 was significantly associated with worse overall survival (OS) of glioma both in TCGA (p < 0.0001) and CGGA (p < 0.0001)." (PMID 34697897, 2022). "For glioma, several studies have shown that GDF15 is associated with many cellular mechanisms, such as apoptosis, migration, and invasion." (PMID 34697897, 2022). "The association between high GDF-15 expression and poor survival of glioma patients was further confirmed following TCGA database interrogation (p = 0.017)." (PMID 32508832, 2020). "Future studies are thus needed in order to better clarify the exact mechanism in which RSU-1 and GDF15 take part in gliomas and evaluate the diagnostic potential of their expression levels." (PMID 31412547, 2019). "Through WGCNA, LASSO and multivariate Cox regression analyses, we identified RAB42, SH2D4A and GDF15 as high-risk hub genes for glioma, and we employed these genes to create a risk model that showed high sensitivity and specificity in prognosticating patients’ 1-, 3-, and 5-year survival." (PMID 37698534, 2023). "This property of GDF-15 may explain the decreased appetite and drastic weight loss in some glioma and GBM patients." (PMID 29467963, 2018). "GTPSCS interacts with p300 to form a functional lactoyltransferase complex in vivo, which enhances histone lactylation levels, modulates GDF15 expression, and ultimately confers radioresistance in gliomas." (PMID 40244246, 2025). "In gliomas, statistically significant correlations were identified between the expression levels of DJ-1, GDF15, and MFGE8 and both tumour grade and the Ki-67 Pi." (PMID 41009755, 2025). "When tumour diameter was evaluated in glioma patients, the expression levels of the DJ-1, GDF15, and MFGE8 genes were found to be elevated compared to those in the control group." (PMID 41009755, 2025). "This modification has been reported to promote glioma proliferation and radiotherapy resistance by regulating oncogenes such as growth differentiation factor 15 (GDF15)." (PMID 40450300, 2025). "When the Ki-67 Pi was evaluated in glioma patients, the expression levels of the DJ-1, GDF15, and MFGE8 genes were elevated compared to those in the control group." (PMID 41009755, 2025). "To validate these findings in vivo, we first generated GDF15-overexpressing murine glioma GL261 cells, and a colony formation assay confirmed their enhanced resistance to radiation in vitro." (PMID 41281763, 2025). "Evaluation of tumour grades in glioma patients revealed that the expression levels of the DJ-1, GDF15, and MFGE8 genes were increased compared to those in the control group." (PMID 41009755, 2025). "In this study, the mRNA expression profiles of DJ-1, GDF15, and MFGE8 genes were analyzed in glioma and meningioma tissues, and their potential associations with clinicopathological parameters were evaluated." (PMID 41009755, 2025). "And in addition to these functions, GDF15 can regulate immune infiltration of glioma and promote stem cell-like phenotype." (PMID 37698534, 2023). "The expression of three risk hub genes in glioma was investigated in the TCGA and CGGA datasets, and RAB42, SH2D4A, and GDF15 were found to be higher expressed in GBM than in LGG." (PMID 37698534, 2023). "In the TCGA and CGGA datasets, the Kaplan-Meier curve showed that RAB42, SH2D4A, and GDF15 significantly affected the prognosis of glioma, with a poor prognosis at high expression." (PMID 37698534, 2023).
glioma (continued). "One study demonstrated that adults with low-grade gliomas and high expression of GDF15 had worse progression-free survival than tumors with low GDF15 expression." (PMID 38146512, 2023). "Among the different tissue types 75% of renal and 83% of CNS cancer cell lines showed a positive correlation of GDF15 and BRD4 induction." (PMID 37495707, 2023). "In this study, we conducted in‐depth analysis of gene expression profiles and in vitro experiments, and found that GDF15 is closely related to the malignant progression, immune microenvironment, and prognosis of glioma." (PMID 34697897, 2022). "Firstly, we detected GDF15 protein levels in four glioma cell lines and HA cell line by Western blot analysis." (PMID 34697897, 2022). "In summary, this study demonstrated that IR directly promotes the secretion of GDF15 from brain ECs and that GDF15 activates the VEGFA promoter in glioma cells through the p-MAPK1/SP1 pathway and consequently enhances angiogenesis in orthotopic brain tumors." (PMID 35280749, 2022). "The findings of this study indicated that radiation-induced HBMVEC-derived GDF15 promoted VEGFA production in U373 glioma cells and consequently enhanced angiogenesis in glioma." (PMID 35280749, 2022). "Overall, these findings demonstrated that GDF15 affected NF‐κB related pathways in glioma, and played an important role in tumor progression." (PMID 34697897, 2022). "The effect of GDF15 on the invasion and migration of glioma cells indicated its key role in tumor progression." (PMID 34697897, 2022). "We found that the migration ability of glioma cell lines was apparently suppressed after transfection with GDF15‐siRNA." (PMID 34697897, 2022). "The results were similar to the analysis of OS, and glioma with low GDF15 expression have better PFS (p < 0.0001)." (PMID 34697897, 2022). "In conclusion, this study confirmed the important role of GDF15 for the malignant progression and immune microenvironment of glioma, especially in LGG." (PMID 34697897, 2022). "GDF15 promotes tumor angiogenesis through a positive feedback loop comprising EC-secreted GDF15, glioma-derived VEGFA, and KDR on ECs." (PMID 35280749, 2022). "Altogether, our findings further indicated GDF15 was closely related to inflammatory response of glioma, especially in LGG." (PMID 34697897, 2022). "GDF15 was closely correlated to inflammatory response, infiltrating immune cells, and immune checkpoint molecules, especially in lower grade glioma (LGG)." (PMID 34697897, 2022). "Gene expression profiles obtained from public glioma datasets were used to explore the biological function of GDF15 and its impact on immune microenvironment." (PMID 34697897, 2022). "Since the status of IDH and chromosome 1p19q had important influence on glioma, the relationship between GDF15 and them was also analyzed." (PMID 34697897, 2022). "Our findings highlight the critical role of GDF15 in regulating cancer cell stemness and provide a rationale for considering GDF15 as a potential target for the treatment of glioma." (PMID 33431816, 2021). "CSCs from glioma biopsies were displayed to release growth differentiation factor 15 (GDF15), which contributes to cancer cell proliferation and immune escape." (PMID 34572009, 2021). "Further, recombinant GDF15 treatment enhanced the sphere-formation capability of U87 TS cells and patient-derived glioma TS cells (G027)." (PMID 33431816, 2021). "GDF15 is highly expressed in tumor tissues and serum of patients with glioma, which contributes to the proliferation of glioma malignancy cells." (PMID 33098235, 2020). "In glioma cells, RNAi-mediated GDF-15 depletion inhibited tumor cell proliferation and enhanced immunogenicity, immune infiltration, and survival in a syngeneic mouse model." (PMID 32508832, 2020). "This study is corroborated by findings from an orthoptic model of glioma in mice, which used RNAi to reduce GDF15 expression in a glioma cell line." (PMID 32310257, 2020).
glioma (continued). "In glioma, increased GDF-15 in cerebrospinal fluid correlated strongly with shorter survival (p = 0.007)." (PMID 32508832, 2020). "To investigate the interplay and possible connection between RSU-1 and GDF15 in glioma cells, we used three different brain cell lines, namely H4, SW1088 and A172, which have different tumoral origin, properties and proteins expression level." (PMID 31412547, 2019). "As this connection, between RSU-1 and GDF15 is not yet well-defined, in the present study, we investigated the interplay between RSU-1 and GDF15 in glioma cell lines and the effect of their expression on glioma cell migration and invasion." (PMID 31412547, 2019). "Here, we provided evidence for the role of GDF15, in glioma cell invasion and for its correlation with RSU-1 in this process." (PMID 31412547, 2019). "The expression of GDF15 and RhoB GTPase has been previously shown to be upregulated in response to compression, and to have increased levels in high grade gliomas rendering them as potential targets for the treatment of this type of cancer." (PMID 31612114, 2019). "This is the first work showing a strong connection between RSU-1 and GDF15 in malignant H4 and A172 cells and provides the basis for their future evaluation as novel anti-invasive targets in gliomas." (PMID 31412547, 2019). "In the present study, we focused on the interplay between RSU-1 and GDF15 and their role in regulating glioma cell invasion using three different glioma cell lines (H4, SW1088 and A172)." (PMID 31412547, 2019). "To increase the understanding of autocrine GDF-15 effects in glioma cells, we analyzed miRNA and mRNA expression profiles by sequencing and array technology, respectively." (PMID 26741507, 2016). "Because of the rather small effects of GDF-15 on the miRNA repertoire, we next aimed at defining the effect of endogenous GDF-15 on the mRNA expression pattern in the same two glioma cell lines, using the Affymetrix GeneChip microarray platform." (PMID 26741507, 2016). "Our findings highlight the complex contributions of GDF-15 to the invasive phenotype of glioma cells and suggest anti-GDF-15 approaches as a promising therapeutic strategy." (PMID 26741507, 2016). "In conclusion, we delineate GDF-15 as a molecule that promotes migration and invasion of glioma cells suggesting a relevant contribution to the malignant phenotype of these tumors." (PMID 26741507, 2016). "To allow for a functional characterization of GDF-15 in glioma cells, we silenced GDF-15 expression using RNA interference in LNT-229 and LN-308 cells." (PMID 26741507, 2016). "In order to define autocrine effects of glioma-derived GDF-15 in detail, we examined the effect of transient GDF-15 gene silencing on several key features of LNT-229 and LN-308 glioma cells." (PMID 26741507, 2016). "Most importantly, two key characteristics of glioma cells, migration and invasion, were impaired upon GDF-15 depletion." (PMID 26741507, 2016). "In contrast, autocrine effects of GDF-15 such as the functional activity of glioma-derived GDF-15 on the tumor cells themselves have remained largely elusive." (PMID 26741507, 2016). "Based on reports in other tumor entities, we defined the role of GDF-15 in glioma cell sensitivity to these treatments." (PMID 26741507, 2016). "In light of these findings, it was observed that the expression levels of DJ-1, GDF15, and MFGE8 genes may be associated with certain key clinical parameters in glioma and meningioma samples, which originate from different cellular lineages." (PMID 41009755, 2025). "GDF15 could enhance the malignancy of gliomas, and elevated levels of GDF15 in cerebrospinal fluid are conspicuously associated with poorer prognoses in GBM." (PMID 40234099, 2025). "Given the findings that GDF15 is required for the activation of STAT3 and tumorigenesis in thyroid cancer and glioma stem cells, we focused whether GDF15 function is mediated through STAT3 signaling in gastric cancer cells." (PMID 36769245, 2023).